ATP1B1 (ATPase Na+/K+ transporting subunit beta 1)
Description:
This is the non-catalytic component of the active enzyme, which catalyzes the hydrolysis of ATP coupled with the exchange of Na(+) and K(+) ions across the plasma membrane. The beta subunit regulates, through assembly of alpha/beta heterodimers, the number of sodium pumps transported to the plasma membrane. Plays a role in innate immunity by enhancing virus-triggered induction of interferons (IFNs) and interferon stimulated genes (ISGs). Mechanistically, enhances the ubiquitination of TRAF3 and TRAF6 as well as the phosphorylation of TAK1 and TBK1. Involved in cell adhesion and establishing epithelial cell polarity.
Synonyms: ATP1B
Tractability: Small molecule: a drug acting on it is in phase 2 or 3 trials; a structure with a bound ligand is known; a high-quality ligand is known; it belongs to a druggable protein family. Antibody: UniProt places it where antibodies can reach, with high confidence; its Gene Ontology location is reachable by antibodies, with high confidence; UniProt predicts a signal peptide or a membrane-spanning region. PROTAC: ubiquitination databases record sites on it; its protein half-life has been measured.
Target class: P-type ATPase; Sodium potassium ATPase; Primary active transporter; Transporter
Safety:
Unwanted effects reported when the protein is acted on. In parentheses: how it was acted on, where the effect was seen, and who reports it.
atrioventricular block (inhibition, acute dosing; renal, cardiovascular; source: Lynch et al. (2017))
cardiac arrhythmia (inhibition, acute dosing; renal, cardiovascular; source: Lynch et al. (2017))
decreased heart rate (inhibition, acute dosing; renal, cardiovascular; source: Lynch et al. (2017))
increased cardiac contractility (inhibition, acute dosing; renal, cardiovascular; source: Lynch et al. (2017))
increased urinary sodium excretion (inhibition, acute dosing; renal, cardiovascular; source: Lynch et al. (2017))
increased urine excretion (inhibition, acute dosing; renal, cardiovascular; source: Lynch et al. (2017))
ventricular fibrillation (inhibition, acute dosing; renal, cardiovascular; source: Lynch et al. (2017))
vomiting (inhibition, acute dosing; renal, cardiovascular; source: Lynch et al. (2017))
Gene: Protein-coding gene on chromosome 1 (169,105,697 to 169,310,992, forward strand). Ensembl gene ENSG00000143153.
Subcellular location: Cell membrane; Apical cell membrane; Cell membrane, sarcolemma
Pathways (Reactome):
Disease: Potential therapeutics for SARS
Hemostasis: Basigin interactions
Muscle contraction: Ion homeostasis
Transport of small molecules: Ion transport by P-type ATPases
Gene Ontology:
Molecular function: ATPase activator activity; ATPase binding; MHC class II protein complex binding; P-type sodium:potassium-exchanging transporter activity; protein binding; protein-macromolecule adaptor activity; transporter activator activity; protein heterodimerization activity; protein kinase binding
Biological process: ATP metabolic process; intracellular potassium ion homeostasis; intracellular sodium ion homeostasis; membrane repolarization; positive regulation of potassium ion import across plasma membrane; positive regulation of sodium ion export across plasma membrane; protein localization to plasma membrane; protein stabilization; sodium ion transmembrane transport; cardiac muscle contraction; cell communication by electrical coupling involved in cardiac conduction; establishment or maintenance of transmembrane electrochemical gradient; intracellular calcium ion homeostasis; membrane repolarization during cardiac muscle cell action potential; potassium ion import across plasma membrane; protein transport into plasma membrane raft; proton transmembrane transport; regulation of cardiac muscle contraction by calcium ion signaling; regulation of gene expression; relaxation of cardiac muscle; sodium ion export across plasma membrane; metal ion transport; potassium ion transport; regulation of calcium ion transmembrane transport; response to hypoxia; and 1 more
Cellular component: apical plasma membrane; extracellular exosome; extracellular vesicle; lateral plasma membrane; lysosomal membrane; membrane; organelle membrane; plasma membrane; sodium:potassium-exchanging ATPase complex; sperm flagellum; T-tubule; intercalated disc; sarcolemma; basolateral plasma membrane; caveola
Genetic constraint (gnomAD): Loss-of-function variants: 3 observed, 39.69 expected, observed/expected ratio (o/e) 0.0756, 90% interval 0.033 to 0.19. The upper end of that interval is the gene's LOEUF score, 0.19, which puts it in group 1 of 6, group 1 being the genes least tolerant of losing a copy. Missense variants: 216 observed, 379.94 expected, observed/expected ratio (o/e) 0.57, 90% interval 0.51 to 0.64. Synonymous variants: 139 observed, 138.77 expected, observed/expected ratio (o/e) 1, 90% interval 0.87 to 1.15.
Homologues: Orthologues: chimpanzee ATP1B1 (99% identical), macaque ATP1B1 (98% identical), rat Atp1b1 (95% identical), mouse Atp1b1 (94% identical), dog ATP1B1 (93% identical), pig ATP1B1 (92% identical), guinea pig ATP1B1 (92% identical), rabbit ATP1B1 (70% identical), tropical clawed frog atp1b1 (66% identical), zebrafish atp1b1b (58% identical), zebrafish atp1b1a (58% identical), Caenorhabditis elegans nkb-2 (28% identical), and 2 more. Paralogues in human: ATP1B2 (39% identical), ATP1B3 (36% identical), ATP1B4 (31% identical), ATP4B (30% identical).
Diseases named in the same sentence as ATP1B1 in open-access papers:
ATP1B1 is named in the same sentence as 68 diseases in open-access papers, as found by Europe PMC text mining. Sharing a sentence is not in itself a finding about the gene and the disease. The quoted sentences say what the papers report.
breast carcinoma (5 papers, 2007 to 2024). "Since ATP1B1 transcript has been reported to be upregulated in response to copper overload, this provides an initial hint that, similar to Commd1, Commd3 deficiency causes changes in copper homeostasis in breast cancer." (PMID 37072858, 2023). "Progestin decreased miR-29 expression relieving the repression of the gene encoding ATPase, Na/K transporting, beta 1 polypeptide (ATP1B1), a direct PR target gene which limits migration and invasion of breast cancer cells." (PMID 22583478, 2012). "Elevated expression of Atp1b1, Spint2, and Acly in AA women breast cancer cells were observed when the expression levels of all AA and CAU women cell lines were compared." (PMID 17472751, 2007). "This evidence suggests that the altered expression levels of CARD10, KLF4, Acly, Atp1b1, and Spint2 may be contributing factors in the higher mortality rates of AA breast cancer patients." (PMID 17472751, 2007). "Altered expression of Atp1b1, CARD 10, KLF4, Spint2, and Acly in AA breast cancer cells was observed when the overall averages of the expression levels of all AA and CAU cancer cell lines were compared." (PMID 17472751, 2007). "Results from this study indicates that altered expression of the genes Atp1b1, CARD 10, KLF4, Spint2, and Acly may play a role in the aggressive phenotype seen in breast cancer in African American women." (PMID 17472751, 2007).
Hypertension (5 papers, 2013 to 2025). The presence of chronic increased pressure in the systemic arterial system. "Reduced expression of miR-192-5p is associated with an increase in Na/K-ATPase function (ATP1B1 gene), which contributes to hypertension and kidney injury." (PMID 31775784, 2019). "The data indicated that several DEGs, including prostaglandin I2 (prostacyclin) synthase (PTGIS), RGS5, selectin E (SELE), endothelin converting enzyme (ECE), and ATPase, Na+/K+ transporting, and beta 1 polypeptide (ATP1B1), were highly associated with hypertensive disease." (PMID 32041970, 2020). "Previous studies have shown that miR-192-5p can prevent hypertension by inhibiting the expression of Atp1b1." (PMID 38907084, 2025). "In the kidney, miRNA-192-5p contributes to protection against hypertension through the target gene ATP1B1 (β1 subunit of Na+/K+-ATPase), and miR-192-5p levels are significantly decreased in humans with hypertension or hypertensive nephrosclerosis." (PMID 32993185, 2020). "In the Milan Hypertensive Rat, an increase in ATP1B1 expression and Na-K ATPase activity in the kidney precedes the onset of hypertension." (PMID 24098465, 2013).
acute myeloid leukemia (3 papers, 2016 to 2025). Acute myeloid leukemia (AML) is a group of neoplasms arising from precursor cells committed to the myeloid cell-line differentiation. "We used several microarray datasets to test the prognostic efficacy of ATP1B1 expression in cytogenetically normal acute myeloid leukemia (CN-AML)." (PMID 26506237, 2016). "Recent studies in acute myeloid leukemia (AML) have revealed that epigenetic silencing of ATP1B1 through promoter‐region DNA methylation and histone modification leads to instability of the Na/K‐ATPase pump, highlighting this pathway as a potential therapeutic target." (PMID 40761481, 2025). "In a recent study, an overexpression of ATP1B1 was shown to predict a poor prognosis in cytogenetically normal acute myeloid leukemia and could be an unfavorable prognostic biomarker." (PMID 30953499, 2019).
leukemia (3 papers, 2016 to 2023). A malignant (clonal) hematologic disorder, involving hematopoietic stem cells and characterized by the presence of primitive or atypical myeloid or lymphoid cells in the bone marrow and the blood. "Our first main finding is that ATP1B1 is more strongly expressed in CN-AML than normal BM, which suggests ATP1B1 plays an active role during the pathogenesis of leukemia." (PMID 26506237, 2016). "Finally, the Oncomine database and GEPIA database showed that the mRNA expression of ATP1B1 and ATP1B3 are widely upregulated in various cancers, including Leukemia, Lung cancer, Lymphoma, Head and neck cancer and so on." (PMID 33868261, 2021).
ovarian carcinoma (3 papers, 2007 to 2023). A malignant neoplasm originating from the surface ovarian epithelium. "Overall survival analysis was performed to investigate the prognostic effects of CPT1A and ATP1B1 in ovarian cancer." (PMID 38003694, 2023). "Even though over-expression of both CPT1A and ATP1B1 enhances the paclitaxel resistance of ovarian cancer cells, a higher CPT1A expression level allows cancer cells the obtention of stronger metastasis ability, while a high ATP1B1 expression level inhibits metastasis." (PMID 38003694, 2023). "Haplotype analyses including all non-redundant SNPs (i.e excluding rs1641536 and rs1641535 in ATP1B1) showed nine haplotypes with frequencies >0.01, with no significant overall association with ovarian cancer risk (global p = 0.42)." (PMID 17411440, 2007). "The abundance of ATP1B1 has recently been found to be a useful tool for the proper reclassification of samples as either tumors of low malignant potential or the invasive tumors of epithelial ovarian cancers." (PMID 17472751, 2007).
prostate carcinoma (3 papers, 2009 to 2025). A carcinoma that arises from epithelial cells of the prostate gland. "We then integrated the results obtained in vitro and with the murine prostate cancer model and identified two proteins consistently altered upon PGC1α perturbation in PCa, ATPase Na + /K+ Transporting Subunit Beta 1 (ATP1B1) and spermidine synthase (SRM)." (PMID 40268923, 2025). "The eight proteins highlighted in this study (KLK3, SORD, SPON2, IMPDH2, ACTN4, ATP1B1, HSPB1, and KHDRBS1) represent a signature associated with AR modulation during the transition from androgen-dependent to castration-resistant prostate cancers." (PMID 29966326, 2018). "ATP1B1, an Na2K-ATPase, was found to be involved in progression and metastasis of prostate cancer." (PMID 19216735, 2009).
cholangiocarcinoma (2 papers, 2022 to 2024). A carcinoma that arises from the intrahepatic biliary tree (intrahepatic cholangiocarcinoma) or from the junction, or adjacent to the junction, of the right and left hepatic ducts (hilar cholangiocarcinoma). "Also, our previous analyses revealed that a subset of cholangiocarcinoma tumors characterized by the ATP1B1-PRKACA fusion, which retains the same PRKACA exons as the DP fusion, express elevated levels of LINC00473." (PMID 38512964, 2024).
liver fibrosis (2 papers, 2022 to 2024). "Endothelial-specific knockout of ATP1B1 resulted in decreased expression of profibrotic factors such as C-X-C motif chemokine ligands 10 and 1 and connective tissue growth factor, while administration of a selective ATP1B1 inhibitor decreased liver fibrosis." (PMID 39180015, 2024). "We identified an enrichment of the ATP1B1 an astrocyte-specific isoform of the Na+/K+-ATPase transmembrane ionic pump, by RNA sequencing analysis of endothelial cells from a mouse liver fibrosis model." (PMID 36072588, 2022). "We identified that the upregulation of ATP1B1 in ECs regulates an inflammatory response and vascular function that contributes to liver fibrosis in NASH mice." (PMID 36072588, 2022). "We then examined the effect of ATP1B1 blockade by the ATP1B1 inhibitor glycoside digoxin, a selective inhibitor of ATP1B1, on liver fibrosis." (PMID 36072588, 2022). "Meanwhile, in vivo animal experiments demonstrate that pharmacological inhibition with digoxin, a selective inhibitor of ATP1B1, halts disease progression in liver fibrosis mice and preserves liver function." (PMID 36072588, 2022). "To investigate the role of ATP1B1 in liver fibrosis, we first examined the changes in ATP1B1 protein levels in patients with cirrhosis and mice with liver fibrosis." (PMID 36072588, 2022). "Collectively, these findings demonstrate that blockade of ATP1B1 halts disease progression in liver fibrosis mice and preserves liver function." (PMID 36072588, 2022). "We found that knockdown of ATP1B1 accelerated endothelial cell proliferation and angiogenesis and that ATP1B1 inhibition with digoxin reduced liver fibrosis in NASH." (PMID 36072588, 2022). "Furthermore, ATP1B1, an astrocyte-specific isoform of the Na+/+-ATPase transmembrane pump, is upregulated in the liver endothelial cells of mice with liver fibrosis." (PMID 39180015, 2024). "Interestingly, ATP1B1 expression levels were also decreased after TMAO treatment, suggesting that ATP1B1 may be involved in the regulation of TMAO on endothelial cell function to attenuate liver fibrosis." (PMID 36072588, 2022). "We identified an enrichment of the ATP1B1, an astrocyte-specific isoform of the Na+/K+-ATPase (NKA) transmembrane ionic pump, by RNA sequencing analysis of endothelial cells from a mouse liver fibrosis model." (PMID 36072588, 2022).
renal fibrosis (2 papers, 2018 to 2022). A final common manifestation of a wide variety of chronic kidney diseases characterized by glomerulosclerosis and tubulointerstitial fibrosis. "ATP1B1 and HIF-1α are also important in the processes of EMT and renal fibrosis." (PMID 29759484, 2018).
(HCMV) infection (1 paper, 2024). "Research has indicated that the interaction between the UL136 protein and ATP1B1 plays an important role in regulating cellular osmotic pressure and intracellular ion homeostasis during human cytomegalovirus (HCMV) infection." (PMID 39591305, 2024).
age-related macular degeneration (1 paper, 2021). Age-related loss of vision in the central portion of the retina (macula), secondary to retinal degeneration. "ATP1B1 encodes an apical Na+/K+ ATPase, whose expression reduces with age and in age-related macular degeneration (AMD)." (PMID 33307245, 2021).
Alzheimer disease (1 paper, 2022). A progressive, neurodegenerative disease characterized by loss of function and death of nerve cells in several areas of the brain leading to loss of cognitive function such as memory and language. "Both ABCA7 and ATP1B1 are candidate biomarkers of the Alzheimer’s disease." (PMID 36094096, 2022). "The top hits of the analyses of multi-omics Alzheimer’s disease datasets include genes ABCA7 and ATP1B1." (PMID 36094096, 2022).
asthma (1 paper, 2023). "Among the differentially co-expressed genes, eight were previously linked to asthma in genome- (MRPL14, ASB3, RHOBTB2) and epigenome-wide (CLC, EPS15, GPI, SSCRB4, STRN4) association studies and five were mentioned in the literature in the context of asthma (SLC19A1, MAEA, CLC, ATP1B1, and RECK)." (PMID 36835202, 2023).
breast tumors (1 paper, 2022). "Among them, we found that ATP1A1, ATP1A2, ATP1B1, and ATP1B3 are highly expressed in normal breast tissue and among them, ATP1A1 and ATP1B1 are upregulated in breast tumors while ATP1A2 is downregulated and ATP1B3 is unchanged." (PMID 36232400, 2022). "Interestingly, ATP1A1 and ATP1B1 isoforms were overexpressed in breast tumors while ATP1A2 was downregulated in breast tumors and ATP1B3 mRNA expression was unchanged." (PMID 36232400, 2022). "In turn, present results suggest that the treatment of patients with OU or possibly other CGs could be pursued only after the molecular characterization of breast tumors has evidenced a high expression of ATP1A3 and a low expression of ATP1A1 and ATP1B1." (PMID 36232400, 2022).
Cerebral ischemia (1 paper, 2018). Restriction of arterial blood supply to the brain associated with insufficient oxygenation to support the metabolic requirements of the tissue. "Ngb effectively scavenged the overproduced ROS after cerebral ischemia and in turn prevented the inhibition of NKA activity that resulted from oxidative stress-modulated Atp1b1 glutathionylation." (PMID 29802248, 2018).
choroidal neovascularization (1 paper, 2018). An eye disorder described by the growth of new blood vessels that originate from the choroid through a break in the Bruch membrane into the sub–retinal pigment epithelium (sub-RPE) or subretinal space. "Importantly, we found that the expression of ATP1B1 was reduced significantly in macula of AMD with CNV (Choroidal Neovascularization) and GA (geographic atrophy) (P < 0.05)." (PMID 30160348, 2018).
CNS cancer (1 paper, 2020). "We compared the expression levels of FAIM2, DLGAP2, ATP1B1 and RALYL using ONCOMINE databases and found that these 4 genes were significantly downregulated in brain and CNS cancer compared with the normal group." (PMID 33323543, 2020).
corneal oedema (1 paper, 2017). "Lack of ATP1B1 may lead to hypertonicity within the cornea and cause the corneal oedema seen in patients suffering from FECD." (PMID 28358029, 2017).
COVID-19 (1 paper, 2021). A disease caused by infection with severe acute respiratory syndrome coronavirus 2. "Our results are in agreement with such studies and indicate that the expression of the two major subunits of the ATP1 gene, namely the ATP1A1 and the ATP1B1, are downregulated in the PBMCs of our COVID-19 patients with low FT3 serum values, as compared to those with normal FT3 serum values." (PMID 34861865, 2021).
developmental delay (1 paper, 2015). "In addition, several deletions that included the ATP1B1 gene were reported in patients with ID/global developmental delay." (PMID 25902260, 2015).
diabetes (1 paper, 2022). "ATP1B1 encodes a subunit of the sodium potassium ATPase, suggesting that DAR in diabetes may elicit a conserved effect on ion transport across nephron segments." (PMID 36068241, 2022).
fibrolamellar hepatocellular carcinoma (1 paper, 2024). A distinctive type of liver cell carcinoma that arises in non-cirrhotic livers and is seen predominantly in young patients. "The fusion of PRKACA and DNAJB1 is dominant and oncogenic in fibrolamellar hepatocellular carcinoma (FLC), while the DNAJB1-PRKACA or ATP1B1-PRKACB fusion is also detected in pancreatobiliary neoplasms." (PMID 38233872, 2024).